IQGAP1 (IQ motif containing GTPase activating protein 1)
Diseases named in the same sentence as IQGAP1 in open-access papers (continued):
Sharing a sentence is not in itself a finding about the gene and the disease.
tumor (94 papers, 2002 to 2025). "No definitive oncogenic mutations have been identified in IQGAPs in tumors; however, missense mutations have been identified that correlate with specific tumor types, further suggesting that IQGAP1 participates in oncogenic processes." (PMID 37892237, 2023). "The clinical data showed that positive IQGAP1 expression was significantly associated with larger tumor size and an advanced tumor-node-metastasis (TNM) stage." (PMID 36320006, 2022). "The loss of IQGAP1 induces gastric hyperplasia in Iqgap1−/− mice, consistent with IQGAP1 acting as a tumor suppressor." (PMID 34439095, 2021). "At 6 months post-infection, MmuPV1-infected Iqgap1+/+ mice developed significantly higher-grade tumor phenotypes than MmuPV1-infected Iqgap1−/− mice, suggesting a role of IQGAP1 in MmuPV1-associated tumorigenesis." (PMID 34068608, 2021). "It is possible that the combined strength of the 4NQO carcinogen treatment and the HPV16 oncoproteins masked any anti-tumor effects resulting from the loss of IQGAP1." (PMID 34068608, 2021). "While we did not observe a significant contribution of IQGAP1 to HPV-associated carcinogenesis using the HPV16 transgenic mouse model, we did demonstrate that IQGAP1 is important for MmuPV1-associated tumor formation using the infection-based model." (PMID 34068608, 2021). "TNBC cell lines and patient tumor tissues differentially phenocopy these mechanisms supporting clinical existence of molecularly distinct variants of TNBC defined by IQGAP1 pathways." (PMID 32655836, 2020). "In our experiments, in all tumor-associated blood vessels, a coimmunolocalization of IQGAP1 and CD31 was observed." (PMID 28098764, 2017). "Because of this association with molecular partners, IQGAP1 contributes to cell fate, polarization, tumorigenesis, migration, tumor progression and angiogenesis." (PMID 28098764, 2017). "The overexpression of IQGAP1 and β-catenin is associated with tumor progression in HCC in vitro and in vivo due to their contributions for cell proliferation and migration." (PMID 26252773, 2015). "Based on our findings, IQGAP1 and β-catenin are usually overexpressed in vitro and in vivo, and their overexpression levels are associated with tumor malignancy degree of HCC." (PMID 26252773, 2015). "The clinical data showed that positive IQGAP1 expression was associated with larger tumor size, advanced tumor-node-metastasis (TNM) stage, poor relapse-free survival (RFS), and overall survival (OS), and positive IQGAP3 expression was associated with poorer tumor differentiation, RFS, and OS." (PMID 36320006, 2022). "Furthermore, we found that, at 6 months post-infection, MmuPV1-infected Iqgap1−/− mice developed significantly less severe tumor phenotypes than MmuPV1-infected Iqgap1+/+ mice, indicating a role of IQGAP1 in MmuPV1-associated HNSCC." (PMID 34068608, 2021). "The regulation of IQGAP1 as a synchronizer expressed in all kind of cells underlying GBM onco-biology could improve expectations for tumor invasion, resistance and recurrence." (PMID 28098764, 2017). "Simultaneously, significant correlations were observed among the DRGs; for example, FLNA was positively correlated with IQGAP1 (R = 0.67, p < 2.2 × 10−16), suggesting potential coordinated functions between these DRGs in tumor regulation." (PMID 40362690, 2025). "IQGAP1 interacts with a variety of receptor tyrosine kinases (RTKs), acting as a central regulator of signaling cascades that promote tumor progression." (PMID 41035668, 2025). "We observed a significant upregulation of IQGAP1 in tumor tissues compared to adjacent para-tumor tissues." (PMID 40093893, 2025). "To assess the clinical significance of IQGAP1, we conducted immunohistochemical staining on 80 pairs of tumor and para-tumor tissue samples." (PMID 40093893, 2025). "Our data also suggest the role of IQGAP1 in modulating proliferative dynamics, possibly indicating distinct subpopulations within the same cell cycle phase in these tumor cells." (PMID 40868059, 2025).
tumor (continued). "Remarkably, PALB2 mutant samples displayed a more homogeneous tumor cell population with strong peripheral IQGAP1 expression and high colocalization with β-tubulin." (PMID 40868059, 2025). "Post-treatment tumor samples exhibited elevated IQGAP1 expression, particularly in patients with poor treatment responses." (PMID 41035668, 2025). "In control samples, fluorescence intensity exclusive for IQGAP1 exhibited a relative intensity of 12.5 ± 2.5% in control tumor cells, 6.5 ± 1.5% specific for PALB2 alone, and co-localization of both markers was observed in only 5.0 ± 1.0% of signals." (PMID 40868059, 2025). "IQGAP1 serves as a scaffold for several critical intracellular signaling pathways that regulate tumor growth, survival, and metastasis." (PMID 41035668, 2025). "By modulating different molecular pathways, IQGAP1 facilitates tumor cell adaptation to chemotherapy, radiotherapy, and targeted therapies, thus contributing to the development of drug resistance." (PMID 41035668, 2025). "For example, the most studied tumor-related actin cytoskeleton protein is IQGAP1, a scaffold protein that interacts with cytoskeletal components." (PMID 38584831, 2024). "The results demonstrated that all 27 disulfrgs, except for NDUFS1, NUBPL, MYH10, and IQGAP1 genes, exhibited significantly higher expression in tumor tissues." (PMID 38831301, 2024). "Studies have found that the high ubiquitination level of IQGAP1 can reduce its expression and its interaction with and activation of Rho-GTPase, thereby inhibiting tumor metastasis." (PMID 38791874, 2024). "IQGAP1’s cellular localization and expression levels impact various signaling systems, and redistribution of IQGAP1 from the cytoplasm to the membrane correlates to tumor grade and poor disease outcome prognosis." (PMID 39357822, 2024). "Most of these downregulated DRGs (except for IQGAP1) were overexpressed in high-grade tumor tissues." (PMID 37325625, 2023). "The colocalization of CD34 (a telocyte marker) with AmotL2, FKBP51, and IQGAP1 in tumor vessels was indicative of a role for these three scaffold proteins in tumor angiogenesis and vascular invasion." (PMID 37415743, 2023). "For example, a study demonstrated that transgenic GLK promotes tumor metastasis and cell migration through IQGAP1." (PMID 37488602, 2023). "Endogenous IQGAP1 and KSR1 also associated with each other in the tumor cell lines of thyroid origin Cal62 and Hth83, demonstrating that this interaction is widespread among different types of cells." (PMID 36791195, 2023). "As in the case of KSR1, IQGAP1 depletion or blockade of its scaffold functions prevents RAS-ERK pathway–driven neoplasia." (PMID 36791195, 2023). "IQGAP1 is involved in the construction of the whole PI k-Akt pathway, and the blocking of its interaction with PI K inhibit tumor cell survival." (PMID 36275458, 2022). "Related literature has shown that GTPase activator protein 1 (IQGAP1) can induce tumor biology based on the regulation of the RAS pathway and participates in diverse cell processes involving cell transfer, propagation, and cycle after binding with actin." (PMID 36120598, 2022). "Subsequently, we divided the 228 patients into eight subgroups based on IQGAP1/2/3 immunohistochemistry of tumor tissues and analyzed RFS and OS curves of nine groups including all patients and eight subgroups." (PMID 36320006, 2022). "The results showed that the patients in tumor tissues with high IQGAP1 expression, low IQGAP2 expression, and high IQGAP3 expression had the shortest survival time, which is consistent with our findings." (PMID 36320006, 2022). "This indicates that IQGAP1-regulated cytoskeletal remodeling plays an aggressive role in tumor progression." (PMID 35785216, 2022). "When co-implanted with colon cancer cells into nude mice, HSCs with reduced levels of IQGAP1 promoted tumor growth, and led to increased levels of TGF-β receptor and myofibroblast activation in the resulting tumors." (PMID 34439095, 2021).
tumor (continued). "In an in vivo tumorigenesis study, MmuPV1-infected Iqgap1+/+ mice developed significantly more severe tumor phenotypes at six months post-infection than MmuPV1-infected Iqgap1−/− mice." (PMID 34068608, 2021). "Together, these results demonstrate that IQGAP1 contributes quantitatively to MmuPV1-induced tumorigenesis, particularly tumor multiplicity and disease severity." (PMID 34068608, 2021). "PLXNA4 inhibits tumor cell migration, induces innate immune responses via working with Toll-like receptor, and is also co-downregulated with IQGAP1 in PC." (PMID 33498739, 2021). "We have previously demonstrated IQGAP2 as a potential tumor-suppressor and noticed a high level of conservation between IQGAP1 and IQGAP2." (PMID 33266355, 2020). "For example, IQGAP1 can stabilise Cdc42 in its GTP-bound form, thereby increasing active Cdc42.18,19 High levels of IQGAP1 are observed in various tumours." (PMID 32632148, 2020). "Collectively, these results suggest that IQGAP1 expression is important in invasion and metastasis of tumor cells from circulation." (PMID 32051509, 2020). "Among the 19 pairs of normal-tumor cases, the somatic mutation frequencies of these genes ranged from 5.3 to 36.8%, with VAV2, TBC1D10C, KIAA0556, and IQGAP1 showing the highest mutation frequencies (green box)." (PMID 31798960, 2019). "IQGAP1 has been reported to interact with the exocyst complex to help drive vesicle tethering in invadopodia during tumor cell invasion downstream of GTPase signaling." (PMID 28455356, 2017). "Enrichment of IQGAP1 in invadopodia suggests an involvement of IQGAP1 in the invasion process of GBM cells and in podosomes of tumor associated macrophages (TAMs)." (PMID 28098764, 2017). "In support of our study, a single study has prospected the role of relative levels of IQGAP1/IQGAP3 in driving epidermal homeostasis towards neoplasia." (PMID 29073199, 2017). "Positive immunostaining for scaffold AmotL2, FKBP51 and IQGAP1 proteins was found in most cells in healthy colon, tumor, healthy liver and metastasized liver." (PMID 28441737, 2017). "IQGAP1 seems to be involved in tumor progression, since its maximum expression is at the growing front of tumor, just at the apical part of the expanding cells." (PMID 28441737, 2017). "The co-localization of CD34 and AmotL2, FKBP51 and IQGAP1 in several vessels is indicative of a role for these three scaffoldings in tumor angiogenesis and/or in vascular invasion." (PMID 28441737, 2017). "Moreover, we uncovered a novel mechanism by which the DNA methylation-associated silence of tumor suppressor miR-124 contributes to the upregulation of IQGAP1, suggesting that targeting the miR-124-IQGAP1 axis may have therapeutic potential for the treatment of invasive ECs." (PMID 26934121, 2016). "IQGAP1 is overexpressed in different tumors other than EC, and its upregulation positively correlates with tumor metastasis." (PMID 26934121, 2016). "IQGAP1 also down-regulates E-cadherin, thereby attenuating cell–cell adhesions and promoting tumor cell invasion." (PMID 26934121, 2016). "In this study, we focused the protein expression level of IQGAP1 and β-catenin in HCC cells and tissues and their associations with tumor malignancy degree, as well as their roles in cell proliferation and migration ability." (PMID 26252773, 2015). "A study in a rat model of oxidative stress-induced hepatotumorigenesis showed a significant stepwise IQGAP1 upregulation at both the transcript and protein levels throughout tumor progression." (PMID 22973521, 2012). "This indicated that RhoC drove tumor proliferation through IQGAP1, specifically through the C-terminal fragment of IQGAP1." (PMID 23145020, 2012). "In contrast, the expression of IQGAP1 was diffusely positive (>10% of tumor cells) in 69/82 (84.1%) HCC specimens (30/30 samples from Brigham and Women's Hospital and 39/52 samples from the TMA)." (PMID 20977743, 2010).
tumor (continued). "IQGAP1 in control samples depicts the typical clear immunofluorescence signal at variable medium to high intensity levels in the periphery of cytosol and plasma membrane of tumor cells and at a lower intensity level in stroma cells." (PMID 40868059, 2025). "Interestingly, merge images in control cases show some tumor cells in which the expression intensity of IQGAP1 (white arrowheads) is prevalent over β-tubulin, showing two well differentiated populations." (PMID 40868059, 2025). "If the same observations follow for cancer cases, a connection between HSPA1A, IQGAP1, and Tsg101 may reveal crucial information on tumor exosome formation and cargo sorting." (PMID 41369326, 2025). "In addition to playing a crucial role in tumor progression, IQGAP1 is involved in other biological processes." (PMID 41035668, 2025). "Tumoral cells showed expression levels of IQGAP1 similar to those reported in the previous section." (PMID 40868059, 2025). "Previous studies have demonstrated that IQGAP1, a multifunctional scaffolding protein involved in cytoskeletal remodeling, signal transduction, and inflammation regulation, plays pivotal roles in various inflammatory disorders and tumor immunity." (PMID 41190071, 2025). "As PALB2 truncation impairs homologous recombination repair and promotes genomic instability, downstream effects on cytoskeletal regulation may enhance the motile and invasive phenotype of tumor cells through some mechanisms other than IQGAP1." (PMID 40868059, 2025). "In control samples, β-tubulin was heterogeneously distributed across the cytosol, and IQGAP1 expression identified distinct subpopulations of tumor cells, some of which displayed the enhancement of IQGAP1 over β-tubulin, suggesting functional compartmentalization and variable migratory potential." (PMID 40868059, 2025). "Interestingly, as seen in the merging, in some tumor cells of the control case, the expression intensity of IQGAP1 (yellow arrowheads) is prevalent over CK7 (15 ± 3.0%) and never in the truncated PALB2 case." (PMID 40868059, 2025). "In addition, we used the xenografts that were injected into BALB/c mice to investigate the possibility that IQGAP1 plays a role in tumor growth." (PMID 38546389, 2024). "Multiple studies have proven that IQGAP1 is significantly associated with the Rho-GTPase pathway, and the binding and regulation of its GRD domain to the Rho-GTPase pathway proteins plays an important role in tumor invasion and metastasis." (PMID 38791874, 2024). "IQGAP1 promotes tumor development by regulating AS of specific pre-mRNAs related to the cell cycle." (PMID 39179991, 2024). "Furthermore, treatment of sgIF loaded HLC9-EVs plus sorafenib effectively reduced the tumor size and the expression of IQGAP1 and FOXM1 in Huh7 xenografts." (PMID 37202772, 2023). "Potentially, inhibitors of IQGAP1 functions could prevent tumor invasion, proliferation, and migration." (PMID 37488602, 2023). "Our results provide new insights into IQGAP1-mediated scaffolding, and suggest that cell-penetrating WW peptides may exert their anti-tumor effects by disrupting the interaction of IQGAP1 with the catalytic subunit of PI 3-kinase." (PMID 37145016, 2023). "Modifications of H698 may thus be worth pursuing as a means to develop IQGAP1 WW peptides and peptidomimetics that have higher affinity for p110α, and therefore might display greater anti-tumor potency as well." (PMID 37145016, 2023). "In contrast, IQGAP1 is overexpressed in tumor tissues at the cytoplasm and cell contact sites." (PMID 36320006, 2022). "IQGAP1 on the cell membrane may make adherent junctions less effective, which would encourage the dissociation and spread of tumor cells." (PMID 36276098, 2022). "RAC1 and IQGAP1 were reported to play key roles in regulating tumor cell adhesion." (PMID 35574392, 2022).
tumor (continued). "It has been suggested that the biological effects of GTPase activator protein 1 (IQGAP1) on tumor cells can be induced by regulating the response of the RAS signaling pathway and binding to actin is contained in diverse processes like cell binding, propagation, circulate, and transfer." (PMID 36120598, 2022). "In the end, we review recent evidence implicating IQGAP1 in tumor-related immune responses." (PMID 34439095, 2021). "However, when we compared tumor multiplicity, MmuPV1-infected Iqgap1+/+ mice developed a significantly higher number of tumors per mouse than in mock-infected Iqgap1+/+ mice." (PMID 34068608, 2021). "The effects on the tumour growth suppression may stem from the interference with another yet unknown binding partner of IQGAP1 as an integral element of its complex scaffolding function." (PMID 34103645, 2021). "IQGAP1 also activates NK-cells and their anti-tumor responses in a mouse model." (PMID 34439095, 2021). "Evidence thus supports tumor suppressive functions of IQGAP1." (PMID 33498739, 2021). "Furthermore, IQGAP1 knockout significantly inhibits extravasation of tumor cells from circulation, possibly involving invadopodial function." (PMID 32051509, 2020). "Moreover, knockdown of IQGAP1 in a xenograft model of esophageal squamous cell carcinoma reduced primary tumor growth, with unclear effects on metastasis." (PMID 32051509, 2020). "In multivariate analysis using Cox proportional hazards models, N1 stage (HR 2.786; 95% CI 1.617–4.800; P < 0.001), poor tumor differentiation (HR 1.969; 95% CI 1.107–3.500; P = 0.021), and high IQGAP1 expression (hazard ratio [HR] 1.880; 95% CI 1.049–3.367; P = 0.034) were correlated with OS." (PMID 31101875, 2019). "In vivo results revealed that IQGAP1 promoted tumor growth and metastasis." (PMID 31101875, 2019). "Using this “self” vs. “missing-self” model, in vivo cytotoxic potential of Iqgap1−/− NK cells was determined through changes in the ratio of RMA/S to RMA tumor cells recovered from the spleens of tumor-bearing mice when compared with WT mice as well as those sufficiently depleted of NK cells." (PMID 29892299, 2018). "The inability of Iqgap1−/− mice to sufficiently clear RMA/S tumors in vivo demonstrates an apparent defect in the ability of Iqgap1−/− NK cells to mediate antitumor immunity in response to this “missing-self” tumor." (PMID 29892299, 2018). "IL-2-cultured Iqgap1−/− NK cells were also able to kill various tumor cells in vitro." (PMID 29892299, 2018). "Moreover, when isolated and co-cultured with various tumor cells, Iqgap1−/− NK cells have significantly reduced cytotoxic potential, which suggests a role for IQGAP1 in mediating NK cell cytotoxicity through a cell-intrinsic mechanism." (PMID 29892299, 2018). "We found that Iqgap1−/− NK cells were unable to mediate tumor killing to the level of WT controls." (PMID 29892299, 2018). "The IQGAP1+ nucleoli, often found throughout the microscopy field, suggests a correlation between IQGAP1 expression and RNA synthesis in tumor cells, which agrees with the previous report in mouse oocyte nucleus, forming a ring around the nucleolus only in transcriptionally active oocytes." (PMID 28441737, 2017). "To test whether miR-124/IQGAP1 axis is clinically relevant in EC, we examined tumor specimens and adjacent normal tissues from 20 EC patients." (PMID 26934121, 2016). "IQGAP1 is a ubiquitously expressed scaffold protein involved in a variety of cellular processes, such as cell motility, cell-cell adhesion, protein trafficking, transcription, neoplasia, and microbial pathogenesis (14, –, 17)." (PMID 27815503, 2016). "Hence, caveolin-1, IQGAP1, or cholesterol-rich membrane microdomains (lipid rafts) are potential therapeutic targets for prevention or treatment of tumor metastasis." (PMID 25924234, 2015).